IL6 (interleukin 6)
Diseases named in the same sentence as IL6 in open-access papers (continued):
Sharing a sentence is not in itself a finding about the gene and the disease.
infection (continued). "Delta and Omicron infection only marginally altered mRNA expression of IL-1β (Delta vs Mock: p = 0.6114; Omicron vs Mock: p = 0.7534), IL-6 (p = 0.1910; p = 0.2619), IL-18 (p = 0.7755; p = 0.6092), TNF-α (p = 0.9080; p = 0.9405) and IFN-α (p = 0.0612; p = 0.2138)." (PMID 36883057, 2023). "Notably, we observed synergistic effects for IL-6 and IL-8 secretion in microglia cells by concomitant RH infection and interferon stimulation." (PMID 37205102, 2023). "Resistin, IL-6, and myoglobin were all positively correlated with each other in fatal infection." (PMID 37598150, 2023). "In contrast, IL-6 was significantly increased on the day of birth in the presence of suspected postnatal infection, and marked elevations were seen on day 2 among infants with isolated concern for postnatal infection." (PMID 37606448, 2023). "DHAV infection could lead to the different expression of various cytokines in young ducklings; for example, the transcription of IL-1β, IL-2, IL-4, IL-6, IL-8, and IL-10 was highly stimulated after infection." (PMID 37391858, 2023). "Similarly, disruption of the IL-6 gene in mice impaired the immune response after infection with the vaccinia virus." (PMID 38053527, 2023). "Interleukin-6 (IL-6), a pro-inflammatory and pleiotropic cytokine secreted by stimulated monocytes and macrophages, mediates a broad range of immune responses after acute biological stress, such as trauma, infection, or inflammation." (PMID 37214473, 2023). "Decreasing Cu absorption could result in decreased synthesis of ceruloplasmin, a protein that allows Cu transport into tissues and is overexpressed during infections and inflammatory processes in response to increased levels of IL-6 and IFN-γ." (PMID 37718435, 2023). "Moreover, it was limited to the first 24 hours post-infection and IL-6 and TNFα transcripts decreased in abundance rapidly after an initial burst 2 hours post-infection, suggesting that cytokine release is actively repressed in infected cells." (PMID 37830871, 2023). "However, at three days post infection, we observed significantly higher levels of IL-6 and IFN-γ in BALF of G184R mutant virus-infected mice." (PMID 37582777, 2023). "However, we noticed that the lungs of Gr1-depleted mice showed augmented levels of cytokines related to Th1 (TNF-α) and Th17 (IL-6 and IL-17) profiles at 2 weeks after infection." (PMID 36776848, 2023). "When Biozzi mice were pre-inoculated with S. aureus (Q154), 10 days prior to infection with P. aeruginosa, there was a significant reduction in P. aeruginosa bacterial burden in the lungs (p = 0.02), and reduced levels of the pro-inflammatory cytokine IL-6." (PMID 37624013, 2023). "Our previous study found that infection with meningitic E. coli can significantly increase the expression of chemokines and cytokines, such as IL-6, IL-1β, TNF-α, CXCL3, CXCL2, and C-C motif chemokine ligand (CCL) 2, and some chemokines remain at high levels in the blood and brain for a long time." (PMID 37445610, 2023). "Additionally, IL-6 is an early acute phase reactant critical to the regulation of the acute-phase response to injury and infection." (PMID 37765178, 2023). "RBAC can also stimulate cytokine secretion in macrophages, especially TNF-α and IL-6, to initiate inflammation during infection and activate autophagy-related proteins (Beclin-1, Atg5, Atg12, Atg16L) for clearing cellular debris and regulating inflammatory responses." (PMID 37687141, 2023). "The oligosymptomatic course of infection probably influenced maternal IL-6 concentrations." (PMID 37685739, 2023). "In addition, if we prepared bacteria by first sonicating and then using a 5μmF (so/5μmF), the expression changes resembled so/sp infection, with marked upregulation of Il1b, Il6, Nos2, and Tnf." (PMID 36852737, 2023).
infection (continued). "In the present study, this suppression or alteration in the response profile could have been ineffective since there was a predominance of pro-inflammatory cytokines, such as IL-6, in the infection-induced microenvironment." (PMID 36897879, 2023). "IL-6 has been shown to be a very sensitive indicator for monitoring infection and prognosis." (PMID 37095536, 2023). "An increased level of IL-6 was observed in the patient who was diagnosed with a postoperative infection after the first postoperative day (318 pg/mL) compared to the value measured at 60 min of the CPB onset (52 pg/mL) and the control value measured before the surgery (49 pg/mL)." (PMID 37189842, 2023). "The IL-6 level was increased by 228%, p < 0.0001 at 12 h compared to 6 h post infection." (PMID 36707891, 2023). "At 3 h pi the IL6 level was almost similar to the level at 0 h post infection." (PMID 36707891, 2023). "Studies on survivors of SARS have shown that lung abnormalities months after infection may induce an atypical mast cell response and increased interleukin-6 and angiotensin-converting enzyme 2 levels in the nervous system, resulting in headaches." (PMID 36674238, 2023). "Using the same infection scheme, we examined whether the protection against a lethal challenge depends on the dose of the primary IL-6 Tg-PbANKA/LISP2 infection." (PMID 37143657, 2023). "This was particularly evident in individuals with past symptomatic infection (designated Group 5): C. burnetii antigen-stimulated whole blood from these individuals showed elevated bulk release of IL-1β as well as increased IL-6 production by monocytes as detected by flow cytometry." (PMID 37885896, 2023). "Surprisingly, RPE cells also secreted the most IL-6 (up to 5400 pg/mL) in response to infection." (PMID 37205102, 2023). "IL-6 is a protein produced by various types of cells, particularly T lymphocytes, macrophages, mature adipocytes and myocytes, in response to tissue damage from trauma, infection or inflammation, exerting both pro-inflammatory and anti-inflammatory effects." (PMID 36836679, 2023). "More broadly, these findings support the potentially pathological role of IL-6 in severe infection." (PMID 36716318, 2023). "Infections and tissue injuries are defended against by IL-6." (PMID 38249419, 2023). "We found that the levels of TNFα, IL-6, and IFNγ were comparable in control and butyrate-treated mice 18 hours post-infection, suggesting that butyrate did not dampen pro-inflammatory cytokine production in the airways during infection." (PMID 37178819, 2023). "IL-6 is emerging as a prominent and early mediator in the initiation and regulation of acute phase protein production and secretion by hepatocytes in response to painful stimuli such as infection." (PMID 37895886, 2023). "The liver produces CRP in response to infection and is induced to do so by IL-6." (PMID 37876930, 2023). "Notably, infection with ZIKVMR766 has been associated with higher rates of animal death, increased virus replication, and elevated levels of TNF-α, IL-6, and IL-1β in the brain." (PMID 37376550, 2023). "A number of studies have shown the induction of IL-6 and its role during the early infection phase." (PMID 36937293, 2023). "In response to LPS, macrophages play an active role in inflammatory responses by releasing pro-inflammatory cytokines, including TNF-, IL-1, and IL-6, as well as inflammatory factors, such as NO, which recruit additional immune cells to infection or tissue injury sites." (PMID 36678181, 2023). "Considering the parameters with the largest effects on the posterior probability of recurrent infection (i.e., IL-6, PCR CT, EGF, IL-8), bacterial burden and type 2 immunity clearly emerged as positive predictors and type 17 immunity as a negative predictor of recurrent CDI." (PMID 36975808, 2023).
infection (continued). "To examine the effect of IL-6 neutralization on the susceptibility of SK-N-SH cells to WNV or JEV infection, we analyzed virus titers in the culture supernatants of infected and antibody-treated cells collected at 12, 24, and 48 hours after infection." (PMID 38053527, 2023). "IL-6 is essential for effective control of acute respiratory viruses and is one of the most significantly differentially expressed cytokines in co- vs. mono-infection." (PMID 37772820, 2023). "A major rise in IL-6 levels was spotted, showing that the infection took place." (PMID 37081055, 2023). "Interleukin-6 (IL-6), a prototypical cytokine that activates the acute phase and immune response, is immediately produced by immune cells such as macrophages and monocytes in response to stresses such as infection or tissue injury." (PMID 37888125, 2023). "For the full year of 2022, IL-6 levels of suspected EOS and EOS-classified newborns (67 cases) were examined in more detail in relation to the increase in CRP levels to assess whether IL-6 can be used as a reliable early infection marker." (PMID 38255366, 2023). "IL-6 is an important pro-inflammatory cytokine that is released during infection or tissue injury; IL-6 is mainly expressed by natural immune cells such as monocyte macrophages, but can also be produced by Th2 cells, vascular endothelial cells, and fibroblasts." (PMID 37009495, 2023). "The infection with LT2 significantly increased plasmatic IL-6 levels." (PMID 38003758, 2023). "Notably, increased levels of IL-6 and IL-8 mRNAs at 0 dpi indicate upregulation of host responses directly after infection." (PMID 37112941, 2023). "It was found that at day 9 post-infection, the inflammatory cytokines IL-12, IL-17 and IL-6 were significantly decreased (p < 0.05), while immunosuppressive mediator IL-4 was increased (p < 0.05) in MS1987-infected mouse lung compared with MSVec-infected mouse lung." (PMID 38029253, 2023). "Interestingly, ZIKVMR766 infection stimulated higher TNF-α and IL-6 levels than mock-infected cells at the initial stage of infection, i.e., 12 hpi (p < 0.001 and p = 0.4567, respectively), whereas ZIKVPE243 failed to induce significant changes." (PMID 37376550, 2023). "When we examined macrophage gene expression after infection with ∆ppsD by qPCR, we found that expression of Il1b, Il6, Nos2, and Tnf was significantly increased compared to infection with WT Mtb, consistent with the idea that PDIM reduces inflammatory signaling." (PMID 36852737, 2023). "We noticed a drastic increase in IL6 level with increasing time points post infection." (PMID 36707891, 2023). "Interestingly, IL-6, which has been proposed to inhibit DC maturation, was only minimally secreted post LOAd732 infection in DCs and LOAd732 induced high levels of CXCL10 comparable to LOAd703." (PMID 37501121, 2023). "We observed that Delta readily penetrated deep into the respiratory epithelium and this was associated with major tissue destruction, high LDH activity, high viral loads and pronounced innate immune activation as observed by intrinsic C3 activation and IL-6 release at infection sites." (PMID 37915577, 2023). "Moreover, a knock-down experiment using a specific siRNA showed that downregulation of ZFP36L1 during the first 6 hours of infection led to an increase in IL-6 transcription." (PMID 37830871, 2023). "Thus, the presence of pro-inflammatory IL-6 at the site of infection helps in the differentiation of Th17 cells." (PMID 36897879, 2023). "Of note, although individuals with COVID-19 infection prior to the 1st vaccination were excluded from this study, we had reported that such individuals showed increased transient IFN-γ, IP-10/CXCL10, TNF-α, and IL-6 responses compared to infection-naïve persons, but only after the 1st vaccination." (PMID 38090597, 2023).
infection (continued). "IL-6 is a mediator of inflammation and activates the acute phase response leading to neutrophil activation, whereby IL-8 is responsible for the recruitment of neutrophils to the site of infection." (PMID 37237836, 2023). "The beneficial effect of IL-6 in the generation of adult T follicular helper (Tfh) cells, which help activate germinal center B cells to differentiate into plasma cells and memory B cells in response to immunization and infection is well recognized." (PMID 36735294, 2023). "Furthermore, the levels of viral load, IFN-dependent and inflammatory cytokines (IFN-β, IFN-γ, TNF-α, and IL-6) mRNA were assessed in the brain tissue of mice at 7 days post infection, also revealing a diminished pathogenicity of GETV-K648A and GETV-R649A." (PMID 38110975, 2023). "The question is whether pre-infection of the NPTr, PAMs and BM-DCs with mycoplasmas and then infection with S. suis increases the expression of two important pro-inflammatory cytokines, IL-6 and CXCL8." (PMID 37513713, 2023). "This suggests that controlling the production of IL-6, instead of IL-6 clearance, may be the key to treating infections." (PMID 36383295, 2023). "Compared to the lungs of the mice infected with the wild-type rJS/875 virus, exposure to the rJS/875-MA, rJS/875-PA S49Y+D347G, rJS/875-PB2 S155N, rJS/875-PA S49Y and rJS/875-PA D347G viruses led to significantly higher levels of the cytokines IL-6 and IL-1β on day 3 post-infection." (PMID 37858267, 2023). "One previous study has indicated that the distinct signature for severe infections includes a double peak of serum IL-6 levels, and high serum levels of IL-8 and IL-1β, which may aid in differential diagnosis between severe infection and CRS51,79." (PMID 36861439, 2023). "In particular, infection with B. bronchiseptica may lead to an up-regulated secretion of proinflammatory IL-6, which can affect metabolism and energy production in the body." (PMID 38066337, 2023). "Increased levels of IL-6 might be exacerbating the tissue pathology during later infections by increasing inflammation followed by cytokine secretion and cellular recruitment." (PMID 36707891, 2023). "However, when the infection occurs in pregnant women, there is an increase in the production of IL-10, IL-6, IL-17, TNF-a, IFN-a, and IFN-g." (PMID 37376620, 2023). "Additionally, reduced IL-6 signalling in both randomised trials and genetic studies) alters both HDL levels and infection risk." (PMID 37814277, 2023). "Similarly, at 12 h post infection, C1q-treated cells exhibited lower gene expression levels of IL-6 (~ −5-fold), IFN-α (~−1.9-fold), IL-1β (~−4.5-fold), and TNF-α (~−4.4-fold)." (PMID 37376569, 2023). "IL-6 is a key cytokine in infection, cancer, and inflammation." (PMID 36985341, 2023). "Moreover, while IL-6 and TNFα transcripts tripled in numbers within 2 hours after the infection, they returned to baseline levels within 6 hours." (PMID 37830871, 2023). "The qRT-PCR results show that the transcription levels of the inflammatory factors IL-1β, IL-6, and IL-8 were significantly increased after PCN033 infection, while the transcription levels of the inflammatory factors IL-1β, IL-6, and IL-8 were significantly decreased after treatment with BA." (PMID 37630686, 2023). "Although, the aim of the current study was not to identify biomarkers, the concomitant increase in LCN2, CRP and IL6, that we found in this study, might aid in recognizing preterm infants experiencing infection." (PMID 37496672, 2023). "We found that MSAD-1 treatment exerted enhanced productions of two inflammatory cytokines, TNF-α and IL-6 in J774A.1 cells in a dose dependent manner, suggesting that it could elicit immune response of innate cells in infection of mycobacteria." (PMID 37901833, 2023).
infection (continued). "Since inflammatory cytokines play important roles in innate immunity, we measured the expression of inflammatory cytokines in the serum of infected mice at day 5 post-infection and observed that in contrast to WT mice the levels of IL-1β were higher but IL-6 were lower in the serum of Xiap−/− mice." (PMID 37347786, 2023). "IL-6 secretion is stimulated during inflammatory response secondary to tissue injury or infection." (PMID 37841263, 2023). "Notably, infection with a swine H3N2 isolate prompted increased IL-6 and IL-1α protein secretion compared to a seasonal human H3N2 virus." (PMID 38179335, 2023). "There was sporadic IL-6 production, which indicates a possible infection." (PMID 35147719, 2023). "Decreased iNOS, TNF-α, IL-6, and IL-12 levels after miR-148a mimic transfection in SL suggests a negative regulatory role of this miR, which can act directly or indirectly in immune responses to infection by L. infantum." (PMID 36719867, 2023). "In contrast, the liver load of IL-6 Tg-PbANKA/LISP2 parasites remained low over the course of infection, except at the 48-h time point, when the amount of IL-6 Tg-PbANKA/LISP2 parasites rose but at levels significantly lower than those obtained for WT PbANKA parasites." (PMID 37143657, 2023). "Moreover, the results displayed that increasing TQN levels significantly (p < 0.05) decreased the expression levels of IL-8, TNF-α, IL-6 and IL-1β genes un like the control group at 96 h post-infection with P. multocida." (PMID 38292130, 2023). "Also, infection of WT microglia in the presence of IL-6 neutralizing antibody completely abrogated neuronal death." (PMID 38322014, 2023). "Both KC and IL-6 serum levels were increased after infection." (PMID 36808423, 2023). "Upregulation of IL-6 and TNF-α expression may be attributed to tissue damage caused by infection or oxidative stress." (PMID 37711631, 2023). "However, infection markedly increased the expression of inflammatory cytokines (IL-6 and TNF-α) and the apoptotic genes (Caspase-3 and BCL2)." (PMID 36875142, 2023). "GN minipigs challenged with necrotoxigenic E. coli O55 (EcO55) without significant signs of enteric infection showed low or undetectable levels of systemic IL-6, but minipigs with significantly expressed clinical signs of enteric infection showed high levels of IL-6 24 h post-infection." (PMID 38003758, 2023). "Furthermore, T. tenax induced the production of IL-6 at a low multiplicity of infection (MOI) in gum, A549, and NCI-H292 cells." (PMID 36971465, 2023). "In addition, MPO showed significant positive correlations with Resistin and IL-6 in fatal infection." (PMID 37598150, 2023). "In the present study, IL-6 and IL-10 mRNA expressions were increased via PCV2b infection in NPTr and iPAM 3D4/21 cells in accordance with previous studies reporting up-regulation of IL-6 in epithelial cells and increased levels of IL-6 and IL-10 in porcine alveolar macrophages (PAMs)." (PMID 37243291, 2023). "IL-6 was found to be involved in IEC induction of productive infection in resting CD4 + T cells." (PMID 37202790, 2023). "The administration of MccY might contribute to higher levels of IL-6 in the cecum, particularly in cases of high-dose infection, through the expansion of intestinal epithelial cells." (PMID 37819128, 2023). "During the acute phase of Schistosoma infection, before parasite oviposition (approximately 5–7 weeks post-infection), immune responses are largely of the CD4+ Th1 type, associated with increased numbers of M1 macrophages that produce IL-12, IL-6, TNF-α and NO." (PMID 36601859, 2023). "Rapid production of IL6 contributes to host defense during infection and tissue damage." (PMID 37799603, 2023). "In addition to participating in inflammatory responses and anti-infection defenses, IL-1β and IL-6 also participate in the development and metastasis of some malignant tumors." (PMID 36992837, 2023).